CTSK (cathepsin K)
Diseases named in the same sentence as CTSK in open-access papers (continued):
Sharing a sentence is not in itself a finding about the gene and the disease.
diabetes (8 papers, 2009 to 2025). "In summary, these data suggest that knocking out cathepsin K deficiency mitigates diabetes-induced cardiac anomalies due to attenuation in calcineurin/NFAT signaling and subsequent reduction in cardiac oxidative stress and apoptosis." (PMID 28821796, 2017). "Genetic deletion of cathepsin K attenuated diabetes-associated changes in cardiac posterior wall thickness, increase in LVEDD and LVESD, as well as the reduction in fractional shortening and heart rate." (PMID 28821796, 2017). "To expand upon our previous findings, we tested the hypothesis that, knockout of cathepsin K protects against diabetes-associated cardiac anomalies." (PMID 28821796, 2017). "Furthermore, cathepsin K deficiency suppressed diabetes-associated myocardial apoptosis, oxidative stress and calcineurin/NFATs signaling." (PMID 28821796, 2017). "Thus, targeting cathepsin K may represent a novel strategy to treat or prevent diabetes-associated cardiac complications." (PMID 28821796, 2017). "Therefore, cathepsin K may represent a potential target in treating diabetes-associated cardiac dysfunction." (PMID 28821796, 2017). "1,25D treatment or FoxO1 knockout rescued the inhibitory effect of diabetes on osteoblastic markers to a large extent, and down‐regulated the expression of Cathepsin K gene (P <.05)." (PMID 33609082, 2021). "Specifically, we showed that knocking out cathepsin K alleviates diabetes-induced hyperglycemia, alterations in energy metabolism, and “normalizes” cardiac structure and functional anomalies." (PMID 28821796, 2017). "Accordingly, in this study, we hypothesized that cathepsin K knockout protects agains cardiac structural and functional alterations induced by diabetes." (PMID 28821796, 2017). "This suggests there may be a protective role of knocking out cathepsin K activity on diabetes-induced cardiac changes." (PMID 28821796, 2017). "Cathepsin K is a protease involved in apoptosis and fibrosis following injury, and it has been linked to cardiovascular disease in chronic kidney disease patients, but notably only in the absence of diabetes." (PMID 41347018, 2025). "Increases in cathepsin K and the ratio of receptor activator of nuclear factor kappa-Β ligand (RANKL) to osteoprotegerin in tibiae were noted in mice with STZ-induced diabetes." (PMID 30413166, 2018). "There was no change in protein expression of AKT or GSK3β for either diabetes or cathepsin K knockout conditions." (PMID 28821796, 2017). "Western blot analysis showed that diabetes dampened phosphorylation of AKT and GSK3β, p-AKT-to-AKT ratio and p-GSK3β-to-GSK3β ratio, and enhanced expression of Bax, Bcl-2, cleaved caspase-3 and TGF-β, which was mitigated in the cathepsin K knockout." (PMID 28821796, 2017). "An increase in bone cathepsin K and in the RANKL/osteoprotegrin (OPG) ratio was noted only in the high-dose group, suggesting that increased diabetes severity may lead to increased osteoclast activity." (PMID 19495918, 2009). "An increase in cathepsin K and in the ratio of RANKL/OPG was noted in high-dose STZ mice, suggesting the possibility that severe diabetes could increase osteoclast activity, something not seen with lower doses." (PMID 19495918, 2009).
lung carcinoma (8 papers, 2017 to 2025). "Our findings demonstrate that these highlyselective inhibitors are nontoxic, effectively inhibit bone resorptionby human osteoclasts, block CTSK activity in cells and their nuclei,and inhibit activity in human lung cancer tissue." (PMID 40151260, 2025). "This study highlightssignificant advancements in designing CTSK inhibitors with potentialclinical applications for lung cancer and osteoclast-related conditions." (PMID 40151260, 2025). "Most genes were up-regulated in systemic sclerosis and down-regulated in lung cancer, except for CTSK and MYLIP." (PMID 33691643, 2021). "Moreover, the inhibitors can selectively block theactivity of CTSK in lung cancer, where it is thought to play a vitalrole in the progression of malignancies." (PMID 40151260, 2025). "Many researchers assessed the potential role of CTSK in lung cancer." (PMID 37198626, 2023). "We focus on reviewing the potential role of CTSK in lung cancer." (PMID 36005209, 2022). "CTSK displays potent endoprotease activity against fibrinogen, plays an important role in extracellular matrix degradation, its counter-regulation in lung cancer and systemic sclerosis may lead to different effects on the extracellular matrix." (PMID 33691643, 2021).
Obesity (8 papers, 2007 to 2026). Accumulation of substantial excess body fat. "Previous studies from our own group and others have documented an elevation of cathepsin K expression/activity in association with adipocyte differentiation, high-fat diet-induced obesity, obesity-associated cardiac dysfunction, cardiac hypertrophy, and heart failure." (PMID 25692548, 2015). "This was supported by a previous study, where dietary sodium butyrate intervention inhibited the expression of genes related to osteoclast differentiation, including cathepsin K in obesity-prone rats." (PMID 38362518, 2024). "Furthermore, in metabolic disorders like T2DM and obesity, upregulated CTSK drives pathological collagen degradation, compromising tissue integrity." (PMID 41939457, 2026). "The obesity related phenotypes of CTSK−/− and CTSL−/− mice are also in agreement with this hypothesis." (PMID 22844403, 2012). "In particular, CTSK−/− and CTSL−/− mice are protected against diet induced obesity." (PMID 22844403, 2012). "The levels of TRAP, CTSK, RANKL/OPG, matrix metalloproteinase-9 (MMP-9), TRAF6, urinary hydroxyproline, and urinary calcium were increased in the obesity-prone rats after consuming a high-fat diet, which was not seen in the obesity-resistant rats." (PMID 38672518, 2024).
bone cancer (7 papers, 2009 to 2025). A primary or metastatic malignant neoplasm affecting the bone or articular cartilage. "An osteolytic phenotype is frequently induced by presence of bone tumors, associated with stimulation of osteoclastogenesis through RANKL expression and cathepsin K activity." (PMID 41216609, 2025). "The overexpression of CTSK derived from bone marrow promotes the occurrence of bone metastasis and contributes to the pathogenesis of bone tumor progression." (PMID 36005209, 2022). "More, in an SCID-hu mouse bone tumor model, cathepsin K was found to interfere with macrophage-regulated inflammatory processes." (PMID 31555270, 2019). "We have used a cathepsin K-degradable linker, therefore enhancing the specific active targeting to bone cancers." (PMID 19381291, 2009). "Together with the cathepsin-K-cleavable system we aim to achieve a more specific drug release and therefore focus the toxicity of the free drugs to the bone tumor sites." (PMID 19381291, 2009). "Cathepsin K is involved in bone resorption and its expression is stimulated by inflammatory cytokines that are released after tissue injury and in bone neoplasms." (PMID 19381291, 2009). "In addition, overexpression of bone marrow-derived CTSK may promote bone metastasis and its participation in the pathogenesis of bone tumour progression." (PMID 38594611, 2024).
osteosarcoma (7 papers, 2011 to 2025). A usually aggressive malignant bone-forming mesenchymal neoplasm, predominantly affecting adolescents and young adults. "GSEA conducted on all genes demonstrated that patients of S-I tended to exhibit more osteoclastic bone resorption (e.g., ACP5, SIGLEC15, CTSK), which was consistent with the clinical manifestations of osteosarcoma at the early stage." (PMID 36874110, 2023). "In this study, there were six patients with chondroblastic-type osteosarcoma, however, two patient showed a good response of neoadjuvant chemotherapy, and their biopsy specimen histology revealed the presence of ≥ 5 Cathepsin K-positive mature osteoclasts." (PMID 33479294, 2021). "Downstream of Akt/mTOR signaling, we report increased expression levels of cathepsin K. TGF beta-induced cathepsin K secretion has been recently reported in human osteosarcoma cells." (PMID 25823658, 2015). "In osteosarcoma, Cathepsin K has been identified as an indicator of metastasis, and patients with lower expression of Cathepsin K have better prognosis." (PMID 21966391, 2011). "Upregulation of cathepsin K in osteosarcomas predicts poor prognosis and disease metastasis." (PMID 38026637, 2023). "The number of investigated patients was very small, however, according to these findings, neoadjuvant chemotherapy might be effective even in patients with chondroblastic type osteosarcoma, when biopsy specimens demonstrated the presence of ≥ 5 Cathepsin K-positive mature osteoclasts." (PMID 33479294, 2021).
ovarian carcinoma (7 papers, 2015 to 2025). A malignant neoplasm originating from the surface ovarian epithelium. "CTSK, in the case of ovarian cancer, shows association with metastases and inferior overall prognosis of EOC (Epithelial ovarian cancer)." (PMID 35057823, 2022). "CTSK is expressed in several tissue carcinomas, including breast, prostate, lung, kidney, colon, stomach and ovarian cancers." (PMID 36005209, 2022). "Other genes such as FAP, CTSK, FBN1, THBS2, SPARC, and COL1A1 are also known to be ovarian cancer associated." (PMID 27843486, 2016). "Moreover, inhibition of CTSK inhibits cell proliferation and distant metastasis of ovarian cancer cells by suppressing epithelial-mesenchymal transition." (PMID 37198626, 2023).
periodontal disease (7 papers, 2017 to 2025). "The findings support the inhibition of cathepsin K by VBX1000 as a new therapeutic approach for mild-to-moderate periodontal disease in dogs." (PMID 41357757, 2025). "Silencing of Ctsk or inhibiting the function of CTSK by ODN was also used to inhibit inflammation and bone loss caused by periodontal diseases." (PMID 34053135, 2021). "Collectively, these results suggest a novel role of CTSK in the paracrine function of osteoclastogenesis-supporting cells in periodontal disease." (PMID 33445732, 2021). "Cathepsin K (CTSK), another member of the cathepsin family, has also been associated with periodontal diseases." (PMID 29622023, 2018). "Beyond the conventional concepts of CTSK function, these results provide novel insights into the role of CTSK in modulating the paracrine function of osteoclastogenesis-supporting cells during periodontal disease development." (PMID 33445732, 2021). "It was reported that mutations of the CTSK gene displayed multiple dental abnormalities, such as hypoplasia of the enamel, obliterated pulp chambers, and periodontal disease, none of which were found among our studied patients." (PMID 34680947, 2021). "The efficacy and safety of a novel cathepsin K inhibitor, VBX1000, were evaluated in client-owned dogs suffering from periodontal disease." (PMID 41357757, 2025). "Cathepsin K (CTSK) is a cysteine protease that is mainly produced from mature osteoclasts and contributes to the destruction of connective tissues and mineralized matrix as a consequence of periodontal disease (PD)." (PMID 33445732, 2021).
lung diseases (6 papers, 2012 to 2026). "Cathepsins play a role in ECM remodelling, with cathepsin D, H and K (CTSD, CTSH and CTSK) being associated with lung diseases." (PMID 23483898, 2013). "The importance of CTSK in pathological lung diseases is not limited to ALI and PF progression." (PMID 40605618, 2025). "On the other hand, ADAM33 interacts with CTSK and CTSV genes, phagosomal cathepsin genes, being related to lung diseases." (PMID 36411793, 2022).
oncocytoma (6 papers, 2021 to 2025). "Cathepsin K, typically associated with EVT, was expressed in all EVT cases but also aberrantly in one oncocytoma." (PMID 40805143, 2025). "In our hands, oncocytoma and chromophobe renal cell carcinoma are negative for cathepsin K (clone 3F9)." (PMID 34069976, 2021). "Both oncocytoma and chromophobe RCC demonstrate CD117 reactivity and are negative for cathepsin K, which is in opposition to the EVT and ESC-RCC immunoprofiles." (PMID 35203531, 2022).
psoriasis (6 papers, 2016 to 2024). An autoimmune condition characterized by red, well-delineated plaques with silvery scales that are usually on the extensor surfaces and scalp. "CTSK is highly expressed in osteoclasts, a type of macrophages involved in bone resorption, and plays a role in autoimmune disorders, such as psoriasis and systemic lupus erythematosus." (PMID 38624208, 2024). "Cathepsin K plays a key role in the development of psoriasis-like lesions in mouse models of psoriasis by affecting Th17 polarization." (PMID 34746142, 2021). "Other cathepsin family members, such as CTSS, CTSK, and CTSD, have been implicated in the pathology of psoriasis." (PMID 30642337, 2019). "Here we investigate for the first time CTSK serum levels to assess bone degradation status in patients with psoriasis." (PMID 27050092, 2016). "Notably, PsA patients exhibit increased cathepsin K serum levels when compared with psoriasis patients and controls, which negatively correlates with calcitonin serum levels." (PMID 34746142, 2021). "In addition it has been suggested that CTSK is involved in development of psoriasis-like skin lesions through TLR-dependent Th17 activation." (PMID 30863397, 2019). "Besides CTX-1/OCN ratios, we determined also the CTX-1/CTSK ratios in psoriasis patients and controls as CTX-1 is a product of collagen type I degradation by CTSK." (PMID 27050092, 2016). "Although, recently CTSK has been found highly expressed in psoriasis patient skin and involved in development of psoriasis-like skin lesions, inflammation and bone erosion in mouse models, we found only significant higher CTSK levels in patients with PsA compared with PsV." (PMID 27050092, 2016).
Stroke (6 papers, 2019 to 2026). Sudden impairment of blood flow to a part of the brain due to occlusion or rupture of an artery to the brain. "Some cathepsin-K inhibitors made their way to clinical trials but had to be discontinued due their side effects on skin, risk of atrial fibrillation, and stroke." (PMID 32117726, 2020). "Although a cathepsin K inhibitor had shown promise in large animal and human clinical studies, treatment with the cathepsin K inhibitor caused off-target effects and increased the risk of stroke." (PMID 31113907, 2019). "An inhibitor of cathepsin K, odanacatib, was shown to prevent pathological bone loss while preserving bone formation but failed in clinical phase III trials due to increased risk of stroke." (PMID 32947946, 2020).
cardiac hypertrophy (5 papers, 2015 to 2023). "Although cathepsin K knockout reduced cardiac hypertrophy, it did not alter cardiac fibrosis associated with aging." (PMID 25692548, 2015). "It has previously been shown that protein levels of cathepsin K, a lysosomal cysteine protease, are elevated in the failing heart and that genetic ablation of cathepsin K protects against pressure overload-induced cardiac hypertrophy and contractile dysfunction." (PMID 25692548, 2015). "Additionally, age-associated cardiac hypertrophy was suppressed by cathepsin K knockout, without altering cardiac fibrosis." (PMID 25692548, 2015).
chordoma (5 papers, 2020 to 2026). Chordomas are rare malignant tumors arising from embryonic remnants of the notochord in axial skeleton. "Its high expression in the invasion fronts of chordoma, compared to chorda dorsalis and chondrosarcoma controls, incriminates Cathepsin K in chordoma's infiltrative growth." (PMID 32733369, 2020). "Thus, we asked whether chordoma cells possess bone-dissolving activity and found that brachyury-positive cells in human chordoma specimens were positive for cathepsin K, a collagenolytic enzyme produced by osteoclasts." (PMID 38652222, 2024). "Recently, a study revisited the chordoma bone-destructive invasive fronts to find cells expressing brachyury, tartrate-resistant acid phosphatase (TRAP/ACP5), and cathepsin K (CatK/CTSK), similarly to osteoclasts in bone resorption capacities." (PMID 39684443, 2024). "We then used immunofluorescence to ask whether brachyury- and TRAP-positive giant cells express cathepsin K. That analysis revealed colocalization of cathepsin K staining with brachyury and TRAP in chordoma cells." (PMID 38652222, 2024).
colon carcinoma (5 papers, 2021 to 2024). "Cathepsin K (CTSK) mediates interactions between intestinal microbiota imbalance and colon cancer, where its overexpression and the presence of M2 TAMs form a feedback loop that worsens prognosis." (PMID 39736788, 2024). "Research conducted employing a mouse model of colon cancer indicated that metastasis-related protease cathepsin K (CTSK), which is secreted by tumors, can be activated by signals from the gut microbiota." (PMID 39421736, 2024). "Microbial dysbiosis has been shown to induce M2 phenotype through cathepsin K (CTSK) mediated TLR4 signaling, thus creating an immunosuppressive milieu and promoting colonic tumor growth." (PMID 33708214, 2021).
COVID-19 (5 papers, 2021 to 2025). A disease caused by infection with severe acute respiratory syndrome coronavirus 2. "This has led Oso and the team to check the affinity of curcumin against COVID-19-associated proteases, such as cathepsin K, COVID-19 main protease, and SARS-CoV 3C-like protease, by performing in silico studies." (PMID 34925017, 2021). "CTSK has been proposed as a potential target for the treatment of COVID-19." (PMID 39130417, 2024). "cathepsin K, COVID-19 main protease, and SARS-CoV 3C-like protease." (PMID 34925017, 2021). "Allicin could form hydrogen bonding with Gly66 of cathepsin K or Gly143 and Ser144 of the COVID-19 main protease, and Thr190 of the SARS-CoV 3C-like protease." (PMID 34925017, 2021). "IPF showed CTSK overexpression in AT2 cells, COPD exhibited NLRP3 activation, and COVID-19 displayed viral defense gene SAMD9 upregulation." (PMID 41122970, 2025). "Literature has suggested that MAPK and TNF-α are potential therapeutic targets for COVID-19 Another high-scoring compound CHEMBL200004 displayed an inhibitory activity against CTSK in biological detection." (PMID 39130417, 2024). "Indeed, most recent proteomic analysis of COVID-19 autopsies suggested an overall upregulation of the cathepsin family members, including CTSB, CTSD, CTSE, CTSH, CTSK, CTSS, and CTSZ, in the lung of the COVID-19 patients." (PMID 34335974, 2021).
Granuloma (5 papers, 2016 to 2025). A compact, organized collection of mature mononuclear phagocytes, which may be but is not necessarily accompanied by accessory features such as necrosis. "Indeed, Cathepsin K has been used as a biomarker to identify micro-granulomas during Crohn’s disease." (PMID 41586350, 2025). "Most granulomas are identifiable on routine staining, although cathepsin K, a protease expressed in activated macrophages, may be of additional value." (PMID 28617305, 2017). "When compared to granuloma periphery or mucosa, CD68+ cells in the granulomata demonstrated increased gene expression in lysosome or macrophage-related genes such as CTSD, CD68, HEXB, ATP6V0A1, CTSK, LIPA, CD63." (PMID 36302964, 2022). "Their study demonstrated the possible involvement of RANKL, TNF-α, IL-33, cathepsin K, and OPG in the development of radicular cysts and periapical granulomas, with emphasis on the highest immunoreactivity of cathepsin in cysts and TNF-α and OPG in granulomas." (PMID 31011287, 2019).